SIRT3 (sirtuin 3)
Diseases named in the same sentence as SIRT3 in open-access papers (continued):
Sharing a sentence is not in itself a finding about the gene and the disease.
metabolic syndrome (continued). "SIRT3-knockout mice placed on a high-fat diet show insufficient fatty acid β-oxidation and are prone to metabolic syndrome, including insulin resistance and hepatosteatosis." (PMID 33499277, 2021). "Sirtuin 3 (Sirt3) is a mitochondrial protein that integrates cellular energy metabolism and plays an important role in preventing metabolic syndrome." (PMID 33924115, 2021). "Little is currently known about Sirt3 expression in the context of sex-related differences in the development of metabolic syndrome." (PMID 32093284, 2020). "Sirt3 plays a role in preventing metabolic syndrome, and is found to be upregulated in response to caloric restriction and exercise, while being downregulated with age, upon an HFD, and in diabetes." (PMID 32093284, 2020). "A single nucleotide polymorphism in the human SIRT3 gene has been correlated with the reduced enzymatic efficiency of SIRT3 and the development of metabolic syndrome." (PMID 30574122, 2018). "Decreased SIRT3 expression has been reported in the patients with metabolic syndrome, non-alcoholic fatty liver disease, pulmonary arterial hypertension and type 2 diabetes." (PMID 27078640, 2016). "SIRT3 deficient mice have been reported to display NASH and perturbation of the SIRT3 activity in mice was associated with the abnormalities similar to metabolic syndrome and NAFLD." (PMID 25195642, 2014). "The SIRT3 plays a critical role in maintaining mitochondrial integrity and protecting against oxidative stress, particularly by regulating mitochondrial dynamics, metabolic syndromes and ROS production." (PMID 41258072, 2025). "Interestingly, p-mTOR was higher in patients with metabolic syndrome than those with different etiology, and, similar to SIRT-3, in metformin-treated than insulin-treated patients." (PMID 30917505, 2019). "Sirt3-deficient (Sirt3−/−)mice have no obvious phenotype but are susceptible to age-linked diseases including metabolic syndrome, cancer, cardiac hypertrophy-fibrosis/CHF, hearing loss, acute renal injury, neurodegeneration, and radiation-induced fibrosis." (PMID 26370974, 2015). "More recently, SIRT3 has gained attention in its particular roles in metabolic syndrome." (PMID 25782072, 2015). "Numerous reports suggest that SIRT3 may act to prevent metabolic maladies such as insulin resistance, metabolic syndrome, and obesity." (PMID 24046746, 2013). "SIRT3 knockout (KO) mice show no obvious phenotypic changes, but are prone to age-linked diseases including metabolic syndrome, cancer, and cardiac failure." (PMID 24046746, 2013). "This indicates that fasting or calorie restriction could reverse the features of metabolic syndrome by activating both SIRT3 and PGC-1α which increase fatty acid oxidation and mitochondrial biogenesis, respectively." (PMID 23840225, 2013). "Importantly, in conditions such as metabolic syndrome and aging, with dysregulated or downregulated SIRT3, supplementation with NAD+ and its precursors, such as NR, could still be beneficial to reverse vascular pathology." (PMID 35453391, 2022). "They crossed SIRT3−/− mice with APP/PSI mice (double-transgenic mouse models of AD expressing a chimeric mouse/human amyloid precursor protein and containing the L166P mutation, both directed to the CNS) and generated APP/PS1/SIRT3−/− mice with metabolic syndrome and amyloid pathology." (PMID 33669988, 2021). "Considering the available data on SIRT3, it would not be difficult to see why a decrease in SIRT3 could lead to metabolic syndrome, increasing the risk of developing atherosclerosis." (PMID 33614337, 2021). "In addition, polymorphisms in the Sirt3 gene are known to correlate with decreased enzyme efficiency and the development of metabolic syndrome in humans, and there may be many links between Sirt3 and oxidative stress." (PMID 34439446, 2021). "Furthermore, higher Sirt3 in BN rat liver may contribute to its resistance to the metabolic syndrome." (PMID 24743600, 2014).
metabolic syndrome (continued). "However, in contrast to this hypothesis of the beneficial effect of SIRT3 downregulation, a recent study reported on the downregulation of SIRT3 expression by a high-fat diet and acceleration of the development of metabolic syndrome by SIRT3 knockout." (PMID 23166782, 2012). "To further understand how metabolic syndrome and amyloid pathology interact, we performed RNA-seq analysis of the brain samples of APP/PS1/Sirt3-/- mice." (PMID 36396721, 2022). "Lack of SIRT3 in experimental animal leads to several age-related diseases, such as cancer, metabolic syndrome, cardiovascular disease, and neurodegenerative diseases." (PMID 27078640, 2016).
renal fibrosis (50 papers, 2017 to 2026). A final common manifestation of a wide variety of chronic kidney diseases characterized by glomerulosclerosis and tubulointerstitial fibrosis. "A study demonstrated that overexpression of SIRT3 in endothelial cells can protect against renal fibrosis by attenuating metabolic reprogramming and the associated mesenchymal transformation." (PMID 40391375, 2025). "It is found that aging exacerbates UUO-induced renal fibrosis, associated with downregulated SIRT3 expression." (PMID 40698425, 2025). "Studies using SIRT3 knockout mice have shown that these mice are more susceptible to renal fibrosis, particularly characterized by high levels of acetylated mitochondrial proteins." (PMID 38294557, 2024). "Deacetylation of mitochondrial proteins by Sirt3 is closely associated with the remission of renal fibrosis." (PMID 38347622, 2024). "SIRT3-mediated deacetylation of PDHE1α thus regulates metabolic reprogramming in PTECs associated with renal fibrosis." (PMID 39000044, 2024). "During the initial stages of renal fibrosis, diminished Sirt3 expression is associated with increased mitochondrial acetylation, and Sirt3-knockout mice display a susceptibility to mitochondrial protein hyperacetylation, leading to exacerbated renal fibrosis." (PMID 39911234, 2024). "SIRT3 deficiency sensitized Ang-II-induced renal fibrosis by promoting differentiation of pericytes into fibroblasts, exacerbating iron overload and accelerating NADPH oxidase-derived ROS formation." (PMID 37196115, 2023). "In vivo study showed that SIRT3 suppression is associated with renal fibrosis, and further knockdown of SIRT3 profound renal fibrogenic phenotype in mice." (PMID 34983623, 2022). "One study showed that inhibiting SIRT3 by administering SIRT3 siRNA in diabetic mice induces renal fibrosis, further indicating that the mechanism is that SIRT3 deficiency induces abnormal glycolysis, which can promote fibrotic programming." (PMID 36142794, 2022). "Increased SIRT3 expression is beneficial in reducing renal EndMT and renal fibrosis caused by accumulation of EndMT‐derived myofibroblasts." (PMID 35560773, 2022). "Our findings will further our understating of the role of SIRT3 in metabolic reprogramming associated with renal fibrosis." (PMID 34518519, 2021). "The deacetylation of PDHE1α by SIRT3 at lysine 385 plays a key role in metabolic reprogramming associated with renal fibrosis." (PMID 34518519, 2021). "Sirt3 knockout mice were susceptible to hyper-acetylated mitochondrial proteins and to severe renal fibrosis." (PMID 34518519, 2021). "SIRT3 deficiency can lead to impaired insulin secretion, renal fibrosis, increased mitochondrial protein acetylation, and increased mitochondrial oxidative stress." (PMID 34769288, 2021). "In the present study, we revealed that deficiency of SIRT3 deteriorated Ang-II-induced renal fibrosis." (PMID 33233553, 2020). "In summary, deficiency of SIRT3 sensitized Ang-II-induced renal fibrosis by enhancing Ang-II-induced pericyte recruitment and pericyte–fibroblast transition, by promoting Ang-II-induced iron overload and by accelerating NADPH oxidase-derived ROS formation." (PMID 33233553, 2020). "In contrast, SIRT3 plays an important role in the endothelial-to-mesenchymal transition (EndoMT) associated with the vascular pathology of renal fibrosis." (PMID 32932720, 2020). "Furthermore, deficiency of SIRT3 can potentially worsen renal insufficiency and promote renal fibrosis." (PMID 38294557, 2024). "Similarly, in an AKI model of ischemia-reperfusion injury, SIRT3 deficiency exacerbated early renal fibrosis." (PMID 37196115, 2023). "In the Ang II-induced hypertension mouse model, SIRT3 knockdown enhances the conversion of pericytes to fibroblasts, while inducing iron overload, decreasing glucose metabolism in cells, and causing ROS production, thus causing kidney tissue damage and aggravating the progression of renal fibrosis." (PMID 36148005, 2022).
renal fibrosis (continued). "SIRT3 knockout also led to iron overloading and enhanced ROS formation in renal cells via NADPH oxidase, further worsening renal fibrosis; in contrast, SIRT3 overexpression protected against kidney injury induced by Ang II." (PMID 40218970, 2025). "In conclusion, these findings demonstrate that SIRT3 plays a crucial role in mediating the protective effects of JT on renal fibrosis and mitochondrial integrity in CKD." (PMID 40144655, 2025). "Studies using SIRT3 knockout or overexpression mouse models have demonstrated that SIRT3 plays a critical role in alleviating renal fibrosis and oxidative stress in hypertensive nephropathy." (PMID 40218970, 2025). "This expanding understanding of the roles of Sirt1, Sirt3, and Sirt6 in renal fibrosis provides potential avenues for targeted therapeutic interventions in kidney diseases." (PMID 38929505, 2024). "These mice developed severe renal fibrosis, while treatment with honokiol, a small-molecule polyphenol isolated from Magnolia grandiflora that activates SIRT3, leads to reduced acetylation and protection against renal fibrosis." (PMID 39000044, 2024). "In contrast, SIRT3 endothelial cell-specific transgenic mice were protected from Ang II-induced renal fibrosis." (PMID 39000044, 2024). "Mice with specific knockdown of Sirt3 in proximal renal tubular epithelial cells (RTECs) were more likely to exhibit increased acetylation of mitochondrial proteins and enhanced renal fibrosis than normal mice." (PMID 38347622, 2024). "Although endothelial cells overexpressing Sirt3 reduced Ang II-induced renal fibrosis and EndoMT, further mechanistic studies revealed that this was achieved through the SIRT3-Foxo3a-peroxidase pathway, thereby maintaining endothelial homeostasis." (PMID 38347622, 2024). "In particular, SIRT3 was involved in the anti-inflammatory effect of Diosmin-induced renal fibrosis." (PMID 38195573, 2024). "We found that Diosmin can suppress the level of inflammation and inhibit the progression of renal fibrosis by upregulating the expression of SIRT3." (PMID 38195573, 2024). "While the protective role of Sirt3 against fibrosis was initially identified in the heart, emerging evidence supports its protective role in renal fibrosis." (PMID 38929505, 2024). "In the early stages of renal fibrosis, decreased Sirt3 expression is accompanied by increased mitochondrial acetylation, and Sirt3 knockout mice are prone to mitochondrial protein hyperacetylation, and severe renal fibrosis." (PMID 38347622, 2024). "In the initial stages of renal fibrosis, decreased expression of SIRT3 is accompanied by increased acetylation of mitochondria isolated from TECs." (PMID 38294557, 2024). "This SIRT3-Foxo3a-catalase pathway performs an essential role in the endothelial-to-mesenchymal transition and renal fibrosis." (PMID 37237500, 2023). "Pharmacological activation of Sirt3 by PAA significantly reduced renal fibroblast activation and interstitial fibrosis, indicating PAA activates Sirt3 against renal fibrosis." (PMID 36470978, 2023). "We further detected the expression of Sirt3 and β-catenin in kidney tissues from patients with renal fibrosis." (PMID 36470978, 2023). "SIRT3 activation is beneficial in the context of kidney injury since its absence in unilateral ureter obstruction (UUO, classical animal model of renal fibrosis) caused exacerbated injury and fibrosis." (PMID 37064892, 2023). "In SIRT3 knockout mice, AngII-induced EndMT and renal fibrosis can be aggravated, while in endothelial-specific transgenic SIRT3 mice, Ang II-induced EndMT and renal dysfunction can be improved." (PMID 36568553, 2022). "The role of SIRT3 in deacetylation of pyruvate dehydrogenase E1α (PDHE1α) is closely related to metabolic reprogramming during renal fibrosis." (PMID 36148005, 2022). "SIRT3, a key regulator of nematocytes, has been increasingly focused on SIRT3 in the fight against renal fibrosis." (PMID 35560773, 2022).
renal fibrosis (continued). "The mitochondrial SIRT3 regulates lipid metabolism and the antioxidant system, and Sirt3 KO mice exhibit hyper-acetylated mitochondrial proteins in PTECs and severe renal fibrosis." (PMID 36611814, 2022). "Overexpression of LSD1 induces renal fibrosis via decreasing SIRT3 expression and activating TGF-β1/Smad3 pathway." (PMID 34983623, 2022). "The rescue experiments confirmed that LSD1 induced renal fibrosis via decreasing SIRT3 expression and activating TGF-β1/Smad3 pathway." (PMID 34983623, 2022). "SIRT1 and SIRT3 can exert protective effects against renal fibrosis by inhibiting inflammatory responses and apoptosis, and by regulating energy metabolism." (PMID 36148005, 2022). "We found that decreased SIRT3 expression was accompanied by increased acetylation in mitochondria that have separated from TECs during the early phase of renal fibrosis." (PMID 34518519, 2021). "Taken together, these results indicate that SIRT3 can counteract the effects of acetylation on mitochondrial metabolism during the progression of renal fibrosis." (PMID 34518519, 2021). "We created C57BL/6J mice with unilateral ureteral obstruction (UUO) to assess the role of SIRT3 in renal fibrosis." (PMID 34518519, 2021). "SIRT3 can prevent hypertensive nephropathy and angiotensin II-induced renal fibrosis in mice through activatory deacetylation of KLF15 protein." (PMID 34899370, 2021). "We treated C57BL/6J male mice with honokiol (HKL), an activator of SIRT3, to determine the role of SIRT3 in renal fibrosis, and assessed changes in acetylation and metabolism in mitochondria." (PMID 34518519, 2021). "The deacetylation of PDHE1α at lysine 385 by SIRT3 plays a key role in metabolic reprogramming in renal fibrosis." (PMID 34518519, 2021). "Masson’s staining showed that knockout of SIRT3 significantly enhanced Ang-II-induced renal fibrosis." (PMID 33233553, 2020). "In the present study, knockout of SIRT3 in mice exhibited increased renal fibrosis together with an upregulation of collagen I expression." (PMID 33233553, 2020). "Our data also shows the effect of HKL to block UUO-induced renal fibrosis through SIRT3-dependent effects." (PMID 31936371, 2020). "Dioscin, a naturally derived triterpenoid saponin, displayed the activity on fructose-induced renal damage via adjustment of Sirt3-mediated oxidative stress, renal fibrosis, lipid metabolism, and inflammation in rats." (PMID 31572199, 2019). "Taken together, the findings revealed that SIRT3 ameliorated renal function and protected against renal fibrosis in AngII-induced hypertensive nephropathy." (PMID 28465484, 2017). "Furthermore, insufficient SIRT3 is functionally promote renal fibrosis by directly deacetylating RUNX1 at H4K12, leading to attenuated glycolytic process, and subsequently robust glycolytic ability and increased production of lactate." (PMID 41694585, 2026). "Interestingly, the administration of honokiol has been found to activate SIRT3, leading to improved acetylation and prevention of renal fibrosis." (PMID 38294557, 2024). "Indeed, SIRT3 knock-out mice display accelerated renal fibrosis mediated by transforming growth factor β1 (TGF-β1) expression and hyperacetylation of glycogen synthase kinase 3 (GSK3β) at the K15 residue." (PMID 39000044, 2024). "In hypertensive kidney injury, Sirt3 expression is significantly reduced, accompanied by an increase in EndoMT induction, ROS, renal fibrosis, and renal inflammatory cell infiltration, as well as decreased telomerase expression, which is also consistent with the findings of Sirt7." (PMID 38347622, 2024). "Moreover, in mice with a fibrogenic phenotype, SIRT3 overexpression in endothelial cells provided protection against diabetes-induced renal fibrosis." (PMID 39911234, 2024).